AKAP19 (A-kinase anchoring protein 19)
Description:
Binds to type I regulatory subunits of protein kinase A (PKA-RI) and anchors/targets them to the plasma membrane.
Synonyms: smAKAP; C2orf88; MGC13057
Tractability: Antibody: UniProt places it where antibodies can reach, with high confidence; its Gene Ontology location is reachable by antibodies, with medium confidence.
Gene: Protein-coding gene on chromosome 2 (189,879,609 to 190,203,484, forward strand). Ensembl gene ENSG00000187699.
Subcellular location: Cell membrane
Gene Ontology:
Molecular function: protein binding; protein kinase A regulatory subunit binding
Cellular component: plasma membrane
Genetic constraint (gnomAD): Loss-of-function variants: 1 observed, 3.78 expected, observed/expected ratio (o/e) 0.26, 90% interval 0.093 to 1.23. That is too few expected variants to judge how well the gene tolerates losing a copy. Missense variants: 116 observed, 121.64 expected, observed/expected ratio (o/e) 0.95, 90% interval 0.82 to 1.11. Synonymous variants: 48 observed, 41.47 expected, observed/expected ratio (o/e) 1.16, 90% interval 0.92 to 1.47.
Homologues: Orthologues: chimpanzee C2BH2orf88 (99% identical), macaque C12H2orf88 (97% identical), rabbit C2orf88 (83% identical), pig C2orf88 (74% identical), mouse 1700019D03Rik (58% identical), rat C9h2orf88 (58% identical).
Diseases named in the same sentence as AKAP19 in open-access papers:
AKAP19 is named in the same sentence as 9 diseases in open-access papers, as found by Europe PMC text mining. Sharing a sentence is not in itself a finding about the gene and the disease.
AKAP19 shares sentences with these, for which no sentence is quoted: cancer (3 papers); ovarian carcinoma (2); breast carcinoma (1); Cardiovascular Disease (1); Cushing syndrome (1); heart failure (1); prostate carcinoma (1); seminoma (1); thymoma (1).